S100A8 (S100 calcium binding protein A8)
Diseases named in the same sentence as S100A8 in open-access papers (continued):
Sharing a sentence is not in itself a finding about the gene and the disease.
tumor (continued). "S100A8 was strongly associated with tumor differentiation (P = 0.009), e.g. tumors with enhanced S100A8 expression levels were frequently well differentiated (64%) compared with 17% in S100A8-negative tumors." (PMID 24885002, 2014). "Because cells exhibit variable sensitivity to S100A8/A9, this discrepancy might be because tumor cells are more sensitive to calprotectin, or because of the eukaryotic origin of the protein used in previous studies." (PMID 25338166, 2014). "Recent in vitro and in vivo studies indicate that S100A8/A9 mediate several pro-tumor responses; the two apparently opposite effects may be dependent on its extracellular concentration and activation of different signaling pathways." (PMID 25298751, 2014). "S100A8/A9-induced inactivation Cdc2 to negatively regulate the G2/M cell cycle progression is suggested to reduce carcinoma growth and may inhibit tumor formation." (PMID 23874958, 2013). "In these tissues, whether increased S100A8/A9 level is a response to tumorigenesis or actually drives tumor development and progression is unclear." (PMID 23874958, 2013). "Some in vitro studies have demonstrated the apoptosis-inducing effects of S100A8/A9 in tumor cells." (PMID 22685372, 2012). "In contrast, no causal link between epithelial-derived S100a8/a9 and the establishment of chronic inflammation and subsequent tumor-development has been demonstrated yet." (PMID 23241281, 2012). "In conclusion, our results suggest that miR-24 may function as a tumor suppressor in LSCC through down-regulation of S100A8, which suggests that miR-24 could serve as a novel potential maker for LSCC therapy." (PMID 22139384, 2012). "In contrast, no causal connection of epithelial-derived S100a8/a9 and the initiation and maintenance of a chronic inflammation and subsequent tumor-development have been demonstrated yet." (PMID 23241281, 2012). "While other members of this family, such as S100A4, S100A7 and S100A13, have been shown to participate under similar conditions, this discussion focuses on S100A8/A9's role in tumorigenesis by reviewing the effects of S100A8/A9 on tumor cells or vascular endothelial cells." (PMID 22685372, 2012). "S100A8 and S100A9, two members of the S100 family of calcium binding proteins, are abundantly produced during acute and chronic inflammation and play an important role in inflammation associated tumor development." (PMID 22359662, 2012). "Moreover, potential secretion of TNFα, VEGF-A and TGF-β1 from primary tumours induced S100A8 and S100A9, which in turn stimulated the enrichment of other inflammatory chemo-attractants." (PMID 23157946, 2012). "Furthermore, S100A8/A9+ MDSCs impair tumor immunity by inhibiting T and NK cell activation, by polarizing immunity toward tumor-promoting type 2 phenotypes, and by inhibiting DC differentiation." (PMID 23166536, 2012). "Indeed, many of the key soluble factors implicated in defining tumor-associated niches, such as VEGF, PlGF, SDF-1α, S100A8, S100A9, SAA3, TNF-α, and TGF-β are HSPG-binding proteins." (PMID 21698156, 2011). "We then went on to investigate whether during malignant tongue/forestomach tumor progression S100A8 inflammatory signaling is in fact activated." (PMID 20857495, 2011). "S100A8/A9 form the compounds that play a role in inducing apoptosis in tumor cells." (PMID 19638242, 2009). "Moreover, Sinha and colleagues found that S100a8/S100a9 produced and secreted by tumour cells binds to Rage on MDSCs and promotes their migration and accumulation through NF-κB signalling pathways." (PMID 19426472, 2009). "The molecular mechanisms of this phenomenon remain largely undefined, however, a recent study demonstrated that tumour-induced and Stat3-dependent up-regulation of S100a8 and S100a9 proteins in myeloid precursor cells are necessary for the accumulation of Gr1+CD11b+MDSCs." (PMID 19426472, 2009).
tumor (continued). "Importantly, dramatically decreased levels of pro-inflammatory mediators (e.g. Ptgs2, S100a8, S100a9, and macrophage inflammatory proteins) and reduced numbers of infiltrating immune cells accompanied impaired tumour formation in Rage-/- animals." (PMID 19426472, 2009). "Similar expression profiles were also seen across all tumour types for S100A8 and S100A9 but this could be attributed to their function in which they form a heterodimer complex." (PMID 18781180, 2008). "Notably, Vegfa macrophages and Proinflammatory macrophages exhibited downregulation of tumor angiogenesis and protumorigenic genes (e.g., Cxcl3, Cxcl1, S100a8, SPP1) and upregulation of immune cell recruitment‐associated genes (e.g., Cxcl9, Ccl5, Ccl8) in mRNA‐treated groups." (PMID 39761175, 2025). "Therefore, immune-related S100A8 expression may serve as a biomarker of the tumor immune microenvironment, warranting further investigation into its prognostic and therapeutic implications." (PMID 41303754, 2025). "Our findings indicate that immune cell-associated S100A8 expression, rather than tumor-intrinsic expression, correlates with patients’ age and histological grade, suggesting that it more accurately reflects the tumor–immune microenvironment." (PMID 41303754, 2025). "In addition, Ly6G+ S100A8/9+ neutrophils surrounded the tumor cells." (PMID 40568104, 2025). "Our findings suggest that immune-associated, rather than tumor-intrinsic, S100A8 expression may hold greater clinical relevance as a biomarker of endometrioid EC." (PMID 41303754, 2025). "S100A8/A9 also activates myeloperoxidase (MPO) activation, releases and accumulates oxidized lipids, and upregulates the fibroblast growth factor receptor (FGFR) pathway in tumor cells, causing tumor cells to be released from dormancy, reactivated, and form new tumor foci." (PMID 38404689, 2024). "Notably, SPP1+TAMs had similar origins to S100A8+monocytes, and BEAM analysis demonstrated that SPP1, CCLs, and CXCLs co-varied with pseudotime, suggesting that S100A8+monocytes recruited by tumor-derived chemokines can reprogram into SPP1+TAMs and perform pro-tumorigenesis functions." (PMID 39323622, 2024). "In addition, we performed a further step GSEA of the six tumor cell subpopulations, and we could observe that C1 S100A8+ TCs were mainly enriched in intracellular zinc ion homeostasis." (PMID 39691708, 2024). "Notably, serum S100A8/A9 levels mirror those of tumor S100A8/A9 in a syngeneic mouse model of TNBC." (PMID 38378783, 2024). "Inhibition of S100A8 could promote cell apoptosis and suppress tumor growth." (PMID 38361783, 2024). "After TFF3 depletion, the expression of M2 markers (CD163, CD206, ARG-1, and IL-10) and S100A4 and S100A8 were remarkably downregulated, which confirmed our hypotheses that iCCA cells induce the M2 phenotype and pro-tumor polarization of resident macrophages by secreting TFF proteins." (PMID 39256888, 2024). "RNA-Seq of bulk tumor samples verified an enrichment of neutrophil-derived genes in combination-treated tumors, specifically, genes associated with pathological activation of neutrophils and MDSC-mediated suppressive function, such as S100a8/a9, Mmp9, and Arg1." (PMID 37988164, 2024). "Moreover, S100A8/A9 concentration lower or higher than a particular concentration might induce the proliferation or apoptosis of tumor cells, respectively." (PMID 37701037, 2023). "Moreover, high levels of S100A8 are considered as an independent prognostic factor for lower survival rate, which correlates with the bottom quartile of M1 macrophages and dendritic cells in the tumor immune microenvironment." (PMID 37174723, 2023). "Therefore, targeting RAGE, HMGB1, and S100A8/A9 will not only reduce immune suppression and facilitate antitumor immunity but may also delay tumor progression by neutralizing the many other mechanisms by which these molecules promote tumor growth." (PMID 36831371, 2023).
tumor (continued). "Interestingly, all these studies found S100A8 staining exclusively in the cytoplasm of tumor cells." (PMID 37450087, 2023). "Lymphovascular invasion and necrosis in the primary tumor were marginally associated with higher S100A8/A9 values in the non-metastatic regional lymph nodes (6.765 ± 6.21 vs. 4.018 ± 5.176, p = 0.0726 and 7.5 ± 6.816 vs. 4.136 ± 5.138 p = 0.0549, respectively) with no other significant associations." (PMID 36835583, 2023). "To validate the possibility of S100A8 targeting against aggressive cancers, we have developed novel multivalent S100A8 competitive inhibitory peptides, and found that S100A8 competitive inhibitory peptides suppress both tumor progression and experimental tumor metastasis." (PMID 36932197, 2023). "Next, we investigated whether S100A8 correlates with HPV tumor status." (PMID 37174723, 2023). "In addition, IL-6 and IL-8 released by fibroblasts could stimulate the upregulation of S100A8 in tumor-infiltrating myeloid cells, and fibroblasts could promote the differentiation of cells in bone marrow into S100A8-expressed TAMs in TME." (PMID 35017463, 2022). "In addition, macrophages also secrete S100A8 to potentially promote tumor immune escape mechanisms." (PMID 34745098, 2021). "However, the anti-tumor activity of CD8+ TILs in S100A8+ ICs (+) group remains unclear since interference by MDSCs can result in CD8+ T cell tolerance." (PMID 33146829, 2021). "We found that several secreted mediators encoding genes notably, LCN2 and S100A8 overexpressed at the distant metastatic site spine (LCN2, 5-fold; S100A8, 6-fold) and bone (LCN2, 5-fold; S100A8, 3-fold) vs. primary tumors in the syngeneic implantation/tumor-resection metastasis mouse model." (PMID 34072157, 2021). "Both proteins S100A8/A9 are able to recruit tumor cells, to maintain inflammatory milieu, promote tumor progression, and create a favorable environment for metastatic niche formation, although the molecular mechanisms underlying their involvement in these processes remain unknown." (PMID 34503307, 2021). "Furthermore, the S100A8/9 heterodimer (calprotectin) is abundant in neutrophils, increases with age in the majority of mouse and human tissues, and displays growth-inhibitory and apoptosis-inducing activities on tumor cells and fibroblasts." (PMID 31936467, 2020). "Furthermore, previous studies have revealed that tumor-infiltrating monocytes and macrophages could promote tumor invasion and migration by upregulating S100A8 and S100A9 expression in cancer cells." (PMID 33193702, 2020). "Secreted S100A8 may regulate inflammatory response within the tumor microenvironment." (PMID 32811814, 2020). "Additionally, TAMs-secreted CXCL1 could recruit MDSCs into the tumor microenvironment, which secreted chemokines including S100A8/9 that enhance cancer cell survival, chemoresistance, metastasis, and pre-metastatic niche formation." (PMID 31803057, 2019). "Therefore, serum S100A8/A9 might be a biomarker depicting the aggressiveness and the metastatic potential of the tumor." (PMID 31806053, 2019). "We found ~10-fold more tumor necrosis factor-α (TNFα) in tumor-infiltrating monocyte/macrophage-conditioned media compared with the conditioned media from naive monocytes/macrophages, suggesting TNFα as a possible candidate for the induction of S100A8 and S100A9." (PMID 27086923, 2016). "Moreover, we demonstrated that S100A8 was probably a tumor promoter of HCC." (PMID 27462864, 2016). "Furthermore, multiple receptors interacting with different S100 proteins or S100A8/A9 heterodimers are expressed by both tumor cells and TAMs (SCARA/B, CD36), preferentially by TAMs (AGER, MSR1, TLR4) or by tumor cells (ERBB2), pointing to extensive functional interactions between both cell types." (PMID 27215396, 2016).
tumor (continued). "Yan Guo found that miR-24 significantly induced cell morphology changes and inhibited cell proliferation and invasion ability in Hep2 cells vitro through down-regulation of S100A8, indicating that miR-24 may function as a tumor suppressor in LSCC by inhibiting S100A8." (PMID 26079642, 2015). "In vivo, these interactions, occurring at the tumor stroma interface, probably contribute in the balance between the reported pro- and anti-tumor effects of S100A8/A9 in PDAC and further investigations of this phenomenon might allow the identification of new potential targets for intervention." (PMID 24670043, 2014). "In addition, S100A8/A9 could also be released by tumor cell necrosis following hypoxia within growing tumors." (PMID 25298751, 2014). "So far no data are available with the levels of S100A8/A9 in tumor mass, but we predict that their levels might never be high enough to cause pro-apoptotic effects on either tumor cells or endothelial cells." (PMID 22685372, 2012). "In addition, S100A8/S100A9 could directly induce proliferation of tumour cells via RAGE ligation, as was shown recently in a cell culture model." (PMID 19426472, 2009). "Forming a common heterodimer structure, S100A8 and S100A9 have been widely reported to participate in multiple biological processes in tumor cells." (PMID 41513624, 2026). "The process of PMN recruitment leads neutrophils to change their behavior by releasing S100A8, S100A9, and Bv8 molecules and forming neutrophil extracellular traps (NETs) that trap tumor cells via integrin β1 binding." (PMID 41463352, 2025). "Other proteins present here are involved in matrix remodeling, which can alter tumor invasiveness (MMP13, S100A8, S100A9, and ELN)." (PMID 40699804, 2025). "S100 proteins, particularly S100A8 and S100A9, have been shown to modulate the tumor microenvironment in ways that promote neovascularization, thereby supporting tumor expansion and metastasis." (PMID 41404073, 2025). "Among the tumor-derived molecules that mediate PMN formation, the S100A8/A9-CD147 axis has emerged as a critical regulator." (PMID 41479915, 2025). "Tumor cell secretions, such as prostaglandin E2 (PGE2) and S100A8/A9 proteins, are critical in promoting MDSC expansion." (PMID 41181705, 2025). "S100A8/A9, an inflammatory heterodimer, binds to CD147 and activates downstream signaling cascades such as ERK and NF-κB, facilitating tumor progression in HNSCC, melanoma, and HPV-positive penile cancer." (PMID 41479915, 2025). "Given their established roles in pre-metastatic remodeling, PMN lung tissue samples from days 11 and 14 post-tumor induction were analyzed for MMP9, fibronectin, and the chemoattractant cytokines S100A8 and S100A9 using ELISA assays." (PMID 40649918, 2025). "This enhanced colony formation was attenuated by S100A8/A9 antibody treatment in both the MCAM WT and MCAM DN groups, further supporting the involvement of S100A8/A9 in MCAM-mediated tumor-promoting effects." (PMID 40924339, 2025). "Neutrophils can be recruited by chemoattractants, such as CXCL8/IL-8, CXCL12/SDF-1, VEGF, S100A8, and S100A9, secreted both from the primary tumor and from stroma cells in the PMN." (PMID 40370456, 2025). "L1, also known as calprotectin, is a heterodimer composed by two calcium-binding proteins S100A8 and S100A9, whose upregulation was reported in different cancers, increasing tumor growth, invasion and metastasis." (PMID 40146757, 2025). "S100A8 and S100A9, small‐molecule calcium‐binding proteins, play pivotal roles in tumor progression." (PMID 40452814, 2025). "Cancer-associated fibroblasts (CAFs) respond to extracellular S100A4, S100A8, and S100A9 by activating pro-inflammatory and pro-fibrotic signaling pathways, which enhance extracellular matrix remodeling and facilitate tumor invasion." (PMID 41404073, 2025).
tumor (continued). "S100A8 promotes the recruitment and accumulation of myeloid-derived suppressor cells (MDSCs), activates NF-κB and MAPK signaling, and facilitates tumor proliferation, invasion, and pre-metastatic niche formation." (PMID 41303754, 2025). "Alternatively, neutrophil-derived MMP9, as well as S100A8 and S100A9, influences tumor cell survival at the metastasizing site." (PMID 39653768, 2025). "These neutrophils enhance PMN formation, facilitating tumor cell extravasation and proliferation through the upregulation of prometastatic proteins such as Bv8, MMP9, S100A8, and S100A9." (PMID 40470380, 2025). "ELISA analysis revealed that tumor spheres released significantly more S100A8/9 and HMGB1 into the tumor microenvironment than adherent cells." (PMID 40647457, 2025). "Chronic inflammation plays a crucial role, as pro-inflammatory mediators—such as S100A8/A9, tumor necrosis factor-α (TNF-α), and the TLR4-NF-κB signaling pathway—recruit myeloid cells and activate the endothelium, facilitating tumor extravasation." (PMID 40909970, 2025). "Specific members such as S100C, S100A8, S100A9, and S100A13 exhibit distinct expression patterns in non-muscle-invasive and muscle-invasive disease, with functional implications for tumor behavior." (PMID 41404073, 2025). "S100A4 promotes angiogenesis and a pro-tumor immune environment, contributing to metastasis through the release of paracrine factors and pro-inflammatory cytokines, whereas S100A8/9, via the RAGE receptor, activates NF-κB and supports tumor cell growth." (PMID 39456655, 2024). "Based on a previous study reporting the role of S100A8/A9 in sustaining the accumulation of MDSC in all lymphoid tissues, we expected that Paquinimod would result in a systemic reduction of the tumor-induced expansion of myeloid cells." (PMID 39497822, 2024). "As expected, the vast majority of immune cell markers, such as CD163, S100A8, CD3, and FOXP3, showed higher expression levels in the TME compartment, while Ki-67, which was detected in proliferative tumor cells, was upregulated in tumor cells." (PMID 38951801, 2024). "Most myeloid components were mainly present in the primary tumor tissue, of which the number of C1QC+TAMs was the highest in the primary tumor among all myeloid cells, followed by S100A8+monocytes, whereas these cells were scarce in the adjacent normal tissue." (PMID 39323622, 2024). "Simultaneously, S100A8/S100A9 activation facilitates leukocyte recruitment, angiogenesis, and tumor migration, along with the enhancement of some genes, including Cxcl1, Ccl5 and Ccl7, Slc39a10, Lcn2, Zc3h12a, Enpp2 and other genes." (PMID 38361783, 2024). "Another interesting functional network concerned the “migration and chemotaxis of neutrophils and myeloid leukocytes” and involved proteins more abundant in S tumor samples, such as S100A9, S100A8, and platelet basic protein (PBP)." (PMID 39195201, 2024). "To investigate the role of S100A8 in GSC self‐renewal and tumor promotion, we transfected GSC 20 and GSC 267 with two independent siRNA sequences separately to silence the S100A8 expression." (PMID 39659236, 2024). "The functional assessment of MDSCs through the analysis of PTGS2, S100A8, IL10, TGFB1, and VEGFA expression provides a comprehensive view of their immunomodulatory activities within the tumor microenvironment." (PMID 39916959, 2024). "S100A8 and S100A9 mainly induce pro-inflammatory and pro-tumor signaling pathways, and it is hard to explain the correlation with apoptosis in this context." (PMID 39575241, 2024). "S100A8 and S100A9 participate in the regulation of the TME affecting tumor genesis, progression, and metastasis through various pathways." (PMID 39195201, 2024). "In contrast, in CP10 (PCP), consisting of type 2 tumor cells, DKK3 staining was weaker than that in CP1, and S100A8, a type 2 tumor cell marker, was observed around the BRAF V600E-stained area." (PMID 39483146, 2024).